SP8 (Sp8 transcription factor)
Description:
Transcription factor which plays a key role in limb development. Positively regulates FGF8 expression in the apical ectodermal ridge (AER) and contributes to limb outgrowth in embryos (By similarity).
Tractability: No criterion of Open Targets' tractability assessment is met for any kind of drug.
Gene: Protein-coding gene on chromosome 7 (20,782,279 to 20,786,886, reverse strand). Ensembl gene ENSG00000164651.
Subcellular location: Nucleus
Subcellular location (Human Protein Atlas): Nucleoplasm
Gene Ontology:
Molecular function: sequence-specific double-stranded DNA binding; DNA-binding transcription factor activity, RNA polymerase II-specific; RNA polymerase II cis-regulatory region sequence-specific DNA binding; sequence-specific DNA binding
Biological process: regulation of transcription by RNA polymerase II
Cellular component: chromatin; nucleus
Genetic constraint (gnomAD): Loss-of-function variants: 10 observed, 14.97 expected, observed/expected ratio (o/e) 0.67, 90% interval 0.41 to 1.13. The synonymous counts are far from expectation, so gnomAD's model fits this gene poorly and the ratio says little. Missense variants: 730 observed, 579.75 expected, observed/expected ratio (o/e) 1.26, 90% interval 1.18 to 1.34. Synonymous variants: 415 observed, 278.77 expected, observed/expected ratio (o/e) 1.49, 90% interval 1.37 to 1.62.
Homologues: Orthologues: chimpanzee SP8 (99% identical), macaque SP8 (99% identical), pig SP8 (98% identical), dog SP8 (98% identical), mouse Sp8 (94% identical), rat Sp8 (94% identical), guinea pig SP8 (89% identical), tropical clawed frog sp8 (73% identical), zebrafish sp8b (72% identical), Drosophila melanogaster luna (14% identical). Paralogues in human: SP9 (58% identical), SP7 (38% identical), SP6 (33% identical), SP5 (28% identical), KLF11 (22% identical), KLF10 (20% identical), KLF5 (18% identical), KLF4 (17% identical), KLF13 (17% identical), KLF12 (16% identical), KLF2 (16% identical), KLF17 (16% identical), and 10 more.
Diseases named in the same sentence as SP8 in open-access papers:
SP8 is named in the same sentence as 26 diseases in open-access papers, as found by Europe PMC text mining. Sharing a sentence is not in itself a finding about the gene and the disease. The quoted sentences say what the papers report.
viral infection (3 papers, 2023 to 2025). "In two other studies of viral infection in rice, the SP8 protein of Southern rice black-streaked dwarf virus (SRBSDV) can interact with OsARF17 and inhibit its ability to bind DNA." (PMID 38033585, 2023). "Both SP8 and P2 interact with the transcriptional activator OsMYB4P, suggesting that in the arms race between rice and viruses, these viral proteins may modulate the transcriptional activation of OsMYB4P to facilitate viral infection." (PMID 40652551, 2025). "To further investigate whether OsRAV15‐mediated resistance was impaired by these distinct viral proteins, we analyzed the function of OsRAV15 on virus infection in the presence of P2, SP8, or M. We first evaluated the effect of OsRAV15 on RSV infection in OsRAV15/P2 hybrid plants." (PMID 39903806, 2025). "Recently, our studies showed that three independently evolved virus proteins with little sequence similarity (SRBSDV SP8, RSV P2, and RSMV M proteins) all regulate the essential components of plant hormone pathways to benefit viral infection and vector feeding." (PMID 39903806, 2025).
Amelia (1 paper, 2014). Congenital absence (aplasia) of one or more limbs. "A progressive reduction in the dose of Sp6 and Sp8 gene products leads to predictable morphology, from syndactyly, to SHFM, oligodactyly, truncation and finally amelia." (PMID 25166858, 2014).
Anosmia (1 paper, 2022). An inability to perceive odors. "We have identified a gene regulatory network, Gsx1/2 – Dlx1/2/5/6 – GAD2/1/Sp8/Sp9 – Tshz1 – Prokr2, which governs OBiN development; mutations of some of these genes result in human Kallmann syndrome with abnormal olfactory function (anosmia or hyposmia)." (PMID 34374948, 2022).
breast carcinoma (1 paper, 2022). "Our validation analysis confirmed that the gain of 5-hmC in TXNL1, BNIPL, CNIH3 and loss of 5-hmC in CHODL, ZBTB16, SP8, and HIC2 in breast cancer samples." (PMID 36230901, 2022).
cognitive decline (1 paper, 2020). "A significant decrease in NMDAR2A protein level was found in SP8 Ct compared to the SR1 Ct, suggesting its participation in the cognitive decline presented by the SAMP8 mouse model." (PMID 32235699, 2020).
diabetes (1 paper, 2023). "By contrast, the expression of PAK2 and Sp8 was significantly increased after diabetes induction." (PMID 37610708, 2023).
gastric cancer (1 paper, 2021). A primary or metastatic malignant neoplasm involving the stomach. "The expression of SP8 was decreased in primary gastric cancer compared with normal gastric mucosa in a recent study." (PMID 34386035, 2021).
Hepatoma (1 paper, 2020). "Second, we have chosen the hepatocellular carcinoma cell line Hep3B because of its low endogenous SP8 expression as a study model for inducible SP8 gain-of function experiments, which might display some tumor properties distinct from HB." (PMID 32824198, 2020).
ischemia (1 paper, 2018). A hypoperfusion of the BLOOD through an organ or tissue caused by a PATHOLOGIC CONSTRICTION or obstruction of its BLOOD VESSELS, or an absence of BLOOD CIRCULATION. "In our study, the trend of Ascl1 expression change was similar to Sp8, no statistically different at day 2 but higher than the contralateral side at day 7, 14, 28 and 60 post-ischemia." (PMID 30524246, 2018).
metastatic disease (1 paper, 2020). "However, as we have analyzed only one paired primary/metastatic tumor, the underlying mechanism for SP8 and FGF8 expression returning to normal in the metastasis, remains uncertain." (PMID 32824198, 2020). "Collectively, these studies convincingly underscore the importance of SP8-induced FGF8 in metastatic disease, as we have shown here for HB." (PMID 32824198, 2020). "In summary, we identified SP8 and FGF8 as key players in aggressive traits of HB and propose SP8 inhibiting drugs as a new effective treatment strategy especially for metastatic tumors." (PMID 32824198, 2020). "Of note, we had one patient with non-metastatic HB at the initial diagnosis, but showed high SP8 and FGF8 levels in the primary tumor suggestive of metastatic disease, who intriguingly developed a lung metastasis eight months after tumor resection." (PMID 32824198, 2020).
osteoporosis (1 paper, 2004). A condition of reduced bone mass, with decreased cortical thickness and a decrease in the number and size of the trabeculae of cancellous bone (but normal chemical composition), resulting in increased fracture incidence. "We speculate that this Sp8 mutation, and other mutations yet to be discovered, may play a role in susceptibility to osteoporosis, and since Sp8 plays an important role in neuropore closure be a candidate gene for spina bifida." (PMID 15533246, 2004). "Another Sp8 cDNA clone was isolated from the osteoblasts of a patient with osteoporosis." (PMID 15533246, 2004).
osteosarcoma (1 paper, 2004). A usually aggressive malignant bone-forming mesenchymal neoplasm, predominantly affecting adolescents and young adults. "Consequently, we used RT-PCR to amplify Sp8 cDNAs from a human osteosarcoma cell line and isolated two transcript variants clones that encode a full-length protein (long isoform) Sp8L and an amino-terminal truncated protein (short isoform) Sp8S, with 508 and 490 residues respectively." (PMID 15533246, 2004). "Since Sp8 was found in human osteosarcoma cell lines and is important in skeletal development we examined the regulation of Sp8 by BMP-2 in the murine pluripotent embryonic cell line, C3H10T1/2 that can be induced to form a chondrogenic/osteoblastic phenotype by treatment with BMPs." (PMID 15533246, 2004).
prostate carcinoma (1 paper, 2014). A carcinoma that arises from epithelial cells of the prostate gland. "By inspection, we also identified at least 10 additional transcription factors within 500 kb of 9 other GWAS loci, that are also reasonable candidates for contributing to prostate cancer risk: SOX13, ZFP36L2, ATOH8, DLX1 & DLX2 (same locus), GATA2, SKIL, SP8, ASCL2, and DPF1." (PMID 24497837, 2014).
psychotic disorder (1 paper, 2013). An abnormal condition of the mind that involves a loss of contact with reality. "Although the association of rs2709722 in Sp8 transcription factor (SP8) was suggestive in the Asian population (P = 2.1×10−7 for psychosis), this signal weakened when the samples size was increased by including data from a Caucasian population (P = 4.3×10−3)." (PMID 23967141, 2013). "In conclusion, we found two loci, PBRM1 (and neighboring genes) and SP8, that were replicated in psychotic disorders in a Japanese population." (PMID 23967141, 2013). "We found 3p21.1 (including PBRM1, strong linkage disequilibrium made it difficult to pinpoint the risk genes) and SP8 as risk loci for BD, SCZ and psychosis." (PMID 23967141, 2013). "Only two SNPs (rs2709722 in SP8 and rs2251219 in PBRM1) within the psychosis set remained significant after the multiple comparison correction (corrected P = 0.037 and 0.048 for rs2709722 and rs2251219, respectively)." (PMID 23967141, 2013).
SARS-CoV infection (1 paper, 2009). "We propose that Sp8 epitope should help in the characterization of mechanisms of virus control and immunopathology in SARS-CoV infection." (PMID 19958537, 2009).
Stroke (1 paper, 2011). Sudden impairment of blood flow to a part of the brain due to occlusion or rupture of an artery to the brain. "As in the post-stroke rat striatum, striatal neuroblasts in CBCM mice do not express a set of TFs specifically involved in the differentiation of medium spiny neurons, but express Sp8, which is also found in SVZ cells fated to become OB interneurons and striatal calretinin interneurons." (PMID 21980380, 2011).
tumor (7 papers, 2018 to 2025). "Although high expression of SP family members has generally been associated with advanced tumor stage, an invasive potential, metastasis, and poor patient survival in many cancers, the exact role of SP8 has remained unclear until now." (PMID 32824198, 2020). "SP8, which encodes specificity protein 1/Klf-like zinc-finger transcription factor, inhibits KARS-mediated transformation and is also a tumor suppressor by itself." (PMID 34386035, 2021). "SP1, SP4, SP7, and SP8, linked to suboptimal or partial chemotherapy responses, exhibited a predominant tumor cell presence (data not displayed)." (PMID 38975339, 2024). "Using KRAB-mediated CRISPR-dCas9 interference directed against FGF8, we could show that FGF8 is essential for the SP8-mediated aggressive tumor behavior." (PMID 32824198, 2020). "Among the most overexpressed genes in tumor cells compared to normal tissue were the transcription factors HOXB9, SIM2, ZIC5, SP8, TFAP2A, FOXE1, HOXB13, and SALL4; the cancer testis antigen CT83; and the cytokine IL23A." (PMID 37228492, 2023). "At the conclusion of the experiment, TKO + TCR SP8 T cells showed significantly improved tumour control compared with mice that received either no T cells or WT + TCR SP8 T cells, and they showed improved survival compared with mice that received no T cells." (PMID 38062131, 2024). "Among the most overexpressed genes in tumor cells compared to normal tissue are genes coding for transcription factors (HOXB9, SIM2, ZIC5, SP8, TFAP2A, FOXE1, HOXB13, and SALL4), cancer testis antigens (CT83), and cytokines activating regulatory Th17 cells (IL23A)." (PMID 37228492, 2023). "In proliferation assays, SP8-induction had no impact on growth rates of the tumor cells over time compared to non-induced cells." (PMID 32824198, 2020). "This allowed the identification of the zinc-finger transcription factor SP8 as a major factor involved in metastatic traits in malignant childhood liver tumors and revealed FGF8 as the main mediator of the SP8-induced aggressive tumor phenotype." (PMID 32824198, 2020). "We could show that SP8 and FGF8 expression was increased only in the primary tumor, but not in the metastasis, as compared to adjacent normal liver." (PMID 32824198, 2020).
infection (6 papers, 2011 to 2025). The state of being infected such as from the introduction of a foreign agent such as serum, vaccine, antigenic substance or organism. "In these infections, loss of CD62Lpos monocytes correlated with the appearance of S.Tm infection of sp8 which shares markers consistent with a classically activated mature macrophage subpopulation (sp8 cells, CD11bpos F4/80pos MHCIIpos)." (PMID 40462990, 2025). "Collectively, these results imply that OsRAV15‐mediated antiviral resistance is subverted by each of the different viral proteins P2, SP8, and M, thus benefiting the infection of their respective RNA viruses." (PMID 39903806, 2025). "Collectively, the evidence strongly implies that SLR1-mediated broad-spectrum antiviral resistance is subverted by viral proteins SP8 and P2, thus allowing the establishment of infection by different RNA viruses." (PMID 36376330, 2022). "By contrast, infections were obtained for the GG13 clone after exposure to the Sp8 strain, but not to the Sp1 strain (Exp." (PMID 21550363, 2011). "In the pathogen exposure treatments, high levels of infection were obtained for the GG4 clone when exposed to the Sp1 strain, but not when exposed to the Sp8 strain (Exp." (PMID 21550363, 2011).
cancer (3 papers, 2015 to 2025). A tumor composed of atypical neoplastic, often pleomorphic cells that invade other tissues. "SP8 belongs to the closely related family of SP zinc-finger transcription factors that are not only critical players during embryonal and postnatal development, but are also often found to be upregulated in many cancers." (PMID 32824198, 2020). "However, a first study on its promoting role in the migration of cortical interneurons has just recently been published, which suggests SP8-induced mechanisms to be also involved in adverse cellular processes in cancer." (PMID 32824198, 2020). "DNA methylation alterations in UNC13A, SP9, GP5, C1QL3, SP8, and VWC2 have not been previously reported in cancer." (PMID 26380585, 2015).
psychiatric disorder (1 paper, 2013). A disorder characterized by behavioral and/or psychological abnormalities, often accompanied by physical symptoms. "Because there are no studies that have examined the association between SP8 and BD/SCZ, further research is needed to better understand the relationship between SP8 and psychiatric disorders." (PMID 23967141, 2013).
SP8 also shares sentences with these, for which no sentence is quoted: hepatoblastoma (2 papers); colorectal cancer (1); Kallmann syndrome (1); liver cancer (1); Parkinson disease (1); spina bifida (1).